FOXP3 (forkhead box P3)
Diseases named in the same sentence as FOXP3 in open-access papers (continued):
Sharing a sentence is not in itself a finding about the gene and the disease.
cholangiocarcinoma (11 papers, 2014 to 2025). A carcinoma that arises from the intrahepatic biliary tree (intrahepatic cholangiocarcinoma) or from the junction, or adjacent to the junction, of the right and left hepatic ducts (hilar cholangiocarcinoma). "Based on our subgroup analysis, it is evident that the association of FoxP3+ Tregs with prognosis significantly varies between gallbladder carcinoma and cholangiocarcinoma." (PMID 38115302, 2023). "The overexpression of FOXP3 has been linked with poor EC prognosis and has been suggested to promote immune escape in cholangiocarcinoma." (PMID 34140005, 2021). "This discrepancy between antibodies against different antigenic sites of Foxp3 suggests the presence of Foxp3 splice variants in cholangiocarcinoma cells." (PMID 25132998, 2014). "Simultaneously, this interaction provokes the accumulation of Foxp3+ regulatory T cells in the tumor microenvironment, enhancing the malignant phenotype of cholangiocarcinoma cells and promoting tumor initiation." (PMID 40070825, 2025). "Alongside, FOXP3 overexpression often occurs in association with CTLA-4 overexpression, which holds unfavorable prognostic value in cholangiocarcinoma." (PMID 33922362, 2021). "Meanwhile, the overexpression of FOXP3 has been reported to play a regulatory role in T cell differentiation while inducing immune escape in cholangiocarcinoma cells." (PMID 34140005, 2021). "MUC1 interacts with EGFR and activates the EGFR/PI3K/Akt signaling pathway, thereby inducing the aggregation of Foxp3+Treg cells, enhancing the malignant phenotype of cholangiocarcinoma cells, and ultimately promoting the growth and metastasis of cholangiocarcinoma." (PMID 40070825, 2025). "To support evidence from our in vivo models, we assessed whether DKK1 might recruit FOXP3 regulatory T cells in human iCCA by analysing transcriptomic Illumina beadchip array data from 104 cholangiocarcinomas (GSE26566)." (PMID 35924447, 2023). "Subgroup analysis of gallbladder carcinoma and cholangiocarcinoma showed that the high infiltration of FoxP3+ Tregs was significantly correlated with the OS of the former (HR = 1.55,95% CI 1.11 to 2.00; P < .001), but not with the OS of the latter (HR = 1.00,95% CI 0.62 to 1.38; P > .05)." (PMID 38115302, 2023). "Moreover, FOXP3 overexpression by cholangiocarcinoma cells correlates with lymph node metastasis and poor survival." (PMID 33922362, 2021). "RT-PCR demonstrated that the cholangiocarcinoma cell line HuCCT1 expresses Foxp3 mRNA." (PMID 25132998, 2014). "Further examination of cholangiocarcinoma cells with four primer sets revealed a Foxp3 splice variant lacking exon 3 that caused a frameshift at the C-terminus creating a novel amino acid, which has been reported in a melanoma cell line." (PMID 25132998, 2014). "To validate the hypothesis that cholangiocarcinoma cells themselves function in immunosuppression similar to Treg cells, we examined the expression of Foxp3 in biliary tract cancer." (PMID 25132998, 2014). "In contrast, no significant prognostic correlation was identified for FoxP3+ Tregs in cholangiocarcinoma, indicating the need for subtype-specific evaluation of their prognostic relevance in biliary tract cancers." (PMID 38115302, 2023). "Previous meta-analysis data showed CD8/Tregs (FOXP3+) ratio produced more impressive hazard ratio than CD8 TILs alone, and Tregs but not CD8 TILs were reported as independent prognostic markers in cholangiocarcinoma." (PMID 29805739, 2018). "Cholangiocarcinoma cells may function as nonprofessional antigen presenting cells that indirectly induce IgG4 reactions via the IL-10-producing cells and/or these may act as Foxp3-positive and IL-10-producing cells that directly induce IgG4 reactions." (PMID 25132998, 2014).
liver disease (11 papers, 2011 to 2025). "We propose that the increased secretion of miR-122 observed in patients with liver diseases may lead to the downregulation of FOXP3-associated targets in Treg, ths contributing to the establishment of a pro-inflammatory milieu in the liver, as reported for miR-122 KO mice and human liver organoids." (PMID 37627157, 2023). "We analyzed the phenotype of hepatic ST2+ Foxp3+ Tregs in immune-mediated hepatitis to assess their impact on liver disease pathology." (PMID 38571949, 2024). "In the present study, we identify a liver cirrhosis TF—miRNA—mRNA network containing 49 TFs, many of which have been previously implicated in liver disease (e.g. ETS1, FOS, FOXP3, FOXA2, and GATA2)." (PMID 28355233, 2017). "CD4+ CD25+ Foxp3 Treg cells contribute to the alleviation of inflammatory liver diseases." (PMID 40918132, 2025). "In fibrotic lung as well as in liver diseases, FOXP3+CD25+ Treg cells limit fibrogenesis." (PMID 35922425, 2022). "By contrast, CD4+CD25+Foxp3+Treg cells contribute to attenuation of liver inflammatory diseases." (PMID 28646856, 2017). "A parallel study from Egypt confirmed our results and described higher FOXP3+ cell numbers and higher FOXP3+/CD4+ ratios in the livers of pAIH compared to non-AIH liver diseases." (PMID 28700730, 2017). "Nevertheless, the expression levels of FoxP3 and TIMP-1 still remained high in the BA liver, suggesting that the expression of these markers may be specifically related to the course of BA over the other inflammatory liver diseases." (PMID 40270513, 2025). "Our results, regarding Foxp3, IL-10, and TGF-β1 expression, imply that nTregs, and not iTregs, could contribute by processes unknown as yet to inflammatory liver disease." (PMID 21772667, 2011).
pneumonia (11 papers, 2017 to 2025). An acute, acute and chronic, or chronic inflammation focally or diffusely affecting the lung parenchyma, caused by an infection in one or both of the lungs (by bacteria, viruses, fungi, or mycoplasma.). "The observed changes in the content of CD4+FoxP3+ lymphocytes in acute pneumonia suggests a possible association with the activity of anti-inflammatory cytokines, primarily interleukin-4." (PMID 41463029, 2025). "MXF-22 has a pronounced immunomodulatory effect, contributing to the restoration of the function of CD4+ FoxP3+ regulatory T cells in acute pneumonia." (PMID 41463029, 2025). "The study showed that the development of acute pneumonia is associated with marked changes in the regulatory mechanisms of the immune response, especially for CD4+FoxP3+ T cells and cytokines involved in maintaining immune homeostasis." (PMID 41463029, 2025). "The change in the proportion of CD4+ FoxP3+ cells makes it possible to more accurately characterize the degree of activation and regulatory potential of the immune system in acute pneumonia and under the influence of the studied drugs." (PMID 41463029, 2025). "Another interesting finding was that the pneumonia severity index in elderly patients was inversely correlated with the proportion of Foxp3+ and Helios+ cells among CD4+ T cells and the level of TGF-β." (PMID 34257746, 2021). "Vitamin A supplement after neonatal S. pneumoniae pneumonia significantly promoted Foxp3+Treg and Th1 productions, decreased Th2 and Th17 cells expressions, alleviated airway hyperresponsiveness (AHR) and inflammatory cells infiltration during AAD." (PMID 32144294, 2020). "Based on these findings, the present study investigated the effects of IVIG on Treg cells derived from immunosuppressed mice with PA pneumonia, via the detection of FOXP3 mRNA expression level in lung tissue and the serum TGF-β concentration." (PMID 28481908, 2017). "In the specific context of pneumonia, CD4+ regulatory T cells (Tregs), characterized by the expression of CD25+ and FoxP3+, serve a central function in suppressing pathological immune activation and promoting tissue repair." (PMID 40649259, 2025). "The MXF-19 complex ((o-Fph)PPhβCD) demonstrated immunomodulatory effects both in metal-induced aseptic inflammation and in the acute pneumonia model, leading to normalization of CD4+ and CD4+CD25+ populations and a reduction in CD4+CD25+FoxP3+ T cells." (PMID 41463029, 2025). "Acute pneumonia is frequently accompanied by immune suppression, particularly affecting T-cell subsets, such as CD4+, CD4+CD25+, and CD4+CD25+FoxP3+, which are critical for immune regulation." (PMID 40649259, 2025). "In animals with the acute pneumonia model, there was a decrease in the number of CD4+ FoxP3+ cells and a violation of the ratio of anti-inflammatory cytokines, including IL-4 and TGF-β." (PMID 41463029, 2025). "Acute pneumonia increased the expression of TNF-α, IFN-γ, IL-6, IL-2 and IL-17 genes, and decreased the expression of Foxp3, IL-10, and TGFβ1 genes in lung tissue homogenate of mice." (PMID 35782123, 2022). "In elderly pneumonia patients, CD4+ T cells from peripheral blood mononuclear cells exhibit reduced Foxp3 and Helios expression in comparison with age- and sex-matched healthy controls." (PMID 34257746, 2021). "Biological evaluation in a rat model of acute pneumonia demonstrated that the complex exerts significant immunomodulatory effects, restoring CD4+ and CD4+CD25+ T-cell populations while reducing immunosuppressive CD4+CD25+FoxP3+ regulatory T cells." (PMID 40649259, 2025). "For selected patients (n=3 in control; n=3 in ICI-pneumonia; n=2 in ICI-pneumonitis), along with chemokine/cytokine receptors, we also investigated expression of key transcription factors including T-bet (Th1), GATA3 (Th2), RoRγT (Th17), and FoxP3 (Treg)." (PMID 33552049, 2020).
adult T cell leukemia (10 papers, 2011 to 2025). "Adult T-cell leukemia/lymphoma is a highly aggressive mature CD4+CD25+FoxP3+ T-cell neoplasm associated with chronic HTLV-1 infection, which affects around 10 million people worldwide." (PMID 41020241, 2025). "MiR-150 is expressed at high levels in mature T and B cells, is downregulated in regulatory T cells (Tregs) through the action of Foxp3, is downregulated in HTLV 1-infected cells, and is upregulated in adult T cell leukemia/lymphoma (ATLL) cells." (PMID 34506539, 2021).
brain tumors (10 papers, 2013 to 2023). "Among ISV + α-CTLA-4 treated mice, left flank tumors showed increased CD8+ infiltration and CD8+:FOXP3+ ratio compared with brain tumors." (PMID 32690669, 2020). "CD8+ and CD4+FoxP3+ T cells were revealed by immunofluorescent staining of brain tumor cryosections and quantitated using Fiji software." (PMID 31462642, 2019). "For example, whereas the density of CD4+Foxp3+ T-cells in the carcinoma areas exhibited a positive correlation with survival after brain tumor resection, their density in stromal areas did not." (PMID 34647108, 2021). "While brain tumors treated with anti-GITR (2a) did not have significantly lower levels of intratumoral CD4 + FoxP3+ cells relative to control, anti-GITR (2a) treatment in flank tumors did result in a significantly diminished proportion of CD4 + FoxP3+ relative to control." (PMID 27190629, 2016).
Cirrhosis (10 papers, 2011 to 2022). A chronic disorder of the liver in which liver tissue becomes scarred and is partially replaced by regenerative nodules and fibrotic tissue resulting in loss of liver function. "Based on these observations, we suggest that potent immunotherapy targeting Th17 cells and CD4+ CD25+ Foxp3+ Tregs and the inhibition of PGE2 secretion from HSC can slow the progress of LF and cirrhosis and other associated complications." (PMID 28399886, 2017). "The upregulation of Foxp3 gene expression was 3.81-fold in HBV-positive cirrhosis when compared with HBV-negative cirrhosis, which was 1.00-fold." (PMID 29201748, 2016). "We found that increased tumor FoxP3+ Tregs was also correlated with cirrhosis background, but more importantly with poorer tumor differentiation." (PMID 21935436, 2011). "We found that increased tumor FoxP3+ cells were correlated with the presence of cirrhosis (P = 0.011) and poorer tumor differentiation (P = 0.003), indicating that the accumulation of these cells is associated with disease progression." (PMID 21935436, 2011). "Comparison of Foxp3 expression between HBV-positive cirrhosis and HBV-positive HCC in the present study observed that upregulation of Foxp3 was more in HBV-positive HCC patients, thus supporting that Foxp3 is associated with the incidence and extent of liver damage in HBV patients." (PMID 29201748, 2016). "For patients with cirrhosis, IHC analyses illustrated significant intrahepatic infiltration of CD3+ T cells, Foxp3+ Tregs, IL-17+ T cells, CD20+ B cells, and CD68+ macrophages in the fibrotic areas." (PMID 35838051, 2022). "Higher mRNA expression of FOXP3 was observed in the HCV and NVHD groups, with the peak observed among patients with cirrhosis." (PMID 27243827, 2016). "At baseline, NAFLD-HCC subjects had a higher percentage of regulatory T cells (Tregs; CD3+CD4+CD25+Foxp3+) compared to NAFLD-cirrhosis and non-NAFLD controls (P < 0.0001)." (PMID 33420074, 2021).
diffuse large B-cell lymphoma (10 papers, 2018 to 2025). "Recently, eTregs were identified in diffuse large B cell lymphoma using dual immunostaining of FOXP3 and CTLA4." (PMID 35438346, 2022). "eTregs were recently revealed using dual immunostaining of FOXP3 and CTLA4 in diffuse large B cell lymphoma." (PMID 35438346, 2022).
endometrial cancer (10 papers, 2012 to 2025). Primary or metastatic malignant neoplasm involving the endometrium (mucous membrane that lines the endometrial cavity). "In contrast, a study on endometrial cancer has reported a positive effect of Foxp3 polymorphisms, where the CA heterozygotes of rs3761548 were found to have a protective role, and the ATT/ATT genotype of rs5902434 was associated with a reduced risk of endometrial cancer." (PMID 39935826, 2025). "Further investigation is warranted to identify the underlying rationale for our findings on the prognostic significance of CD25+FOXP3+CD45RA− Treg cells in endometrial carcinoma." (PMID 39232704, 2024). "CD8+ T cells are known to inhibit tumor angiogenesis by secreting IFN-γ, whereas the presence of CD25+/FOXP3+ tumor-infiltrating lymphocytes reportedly correlates with promoting intratumoral angiogenesis in multiple sorts of cancer including endometrial cancer." (PMID 39232704, 2024). "All these findings are consistent with the literature as CD4, CD8, FoxP3, and PD1 are inflammation markers, and POLE-mutated endometrial carcinomas, usually with a better prognosis than POLE WT, with higher abundance of A1 areas, are described to have large lymphocyte populations." (PMID 35217454, 2022). "In addition, a high cytotoxic T-lymphocyte/regulatory T-lymphocyte (CD8/FOXP3) ratio has been described to be correlated to improved survival in type I endometrial cancer." (PMID 22295114, 2012). "Using a high-grade endometrial carcinoma patient cohort, NaroNet found, among other TMEs that could be explored, a local phenotype expressing CD8, PD1, and FOXP3 whose high abundance was associated with the POLE mutation, while achieving a prediction accuracy of 93.75%." (PMID 35217454, 2022). "We performed multiplexed immunofluorescence and quantitative image analyses of CD25, FOXP3, CTLA4, and CD45RA in tumor specimens from 176 consecutive patients treated at our institution for primary endometrial carcinomas." (PMID 39232704, 2024). "We performed multiplexed immunofluorescence and quantitative image analysis for Treg markers, CD25, FOXP3, CTLA4, and CD45RA, in tumor tissues from 176 patients with endometrial carcinomas." (PMID 39232704, 2024). "High expressions of FOXP3 and CD25 are reported to be associated with chemoresistance in other sorts of malignancies, while not yet investigated in endometrial cancer." (PMID 39232704, 2024). "CD25+FOXP3+CD45RA− effector Treg tumor infiltration may serve as a useful prognostic biomarker and a potential target for immunotherapeutic manipulation of tumor chemosensitivity by novel management for advanced/recurrent endometrial carcinomas." (PMID 39232704, 2024).
Hyperglycemia (10 papers, 2012 to 2024). An increased concentration of glucose in the blood. "In addition, one clinical study reported an increase of CD4+Foxp3+CD39+ Treg cells in PBMCs from overweight T2DM patients associated with hyperglycemia, and we observed an elevated level of CD39 among T cells, B cells, and monocytes." (PMID 36686486, 2022). "We show that the transient loss of Foxp3+ Treg cells in prediabetic NOD.DEREG mice is sufficient to precipitate severe insulitis and persistent hyperglycemia within 5 days after DT administration." (PMID 34447385, 2021). "The level of FOXP3 was markedly elevated in patients with PE who hold abnormal maternal lipids, hyperglycemia, and high BMI." (PMID 33317466, 2020). "Since our model could be hyperinsulinemic due to prolonged state of hyperglycemia, as previously reported, the alterations of Gata3 (Th2) and Foxp3 (Treg) expression found in the present study could be indirectly induced through an insulin-dependent pathway." (PMID 26207186, 2015). "We examined the differentiation of CD4+ lymphocytes by measuring the master genes, including the Tbx21 for Th1, the Rorc for Th17, Gata3 for Th2, and Foxp3 for Treg to evaluate whether hyperglycemia and endotoxemia synergistically modulate the balance between pro- and anti-inflammatory responses." (PMID 26207186, 2015). "Next, hyperglycemia contributes to increased expression of IL-6 and TGF-β that synergistically down regulate FoxP3 at the post-translational level by promoting FoxP3 protein degradation in Tregs." (PMID 30804929, 2019). "The RAG2 KO, RIP-HA Tg recipients developed hyperglycemia by 8–10 days after cell transfer, whereas those receiving either CD4+ (Foxp3-GFP) +/− T-reg cells from the same F1 donors or CD4 splenic T-reg cells from Foxp3-GFP+/+ Tg parental mice did not." (PMID 22723880, 2012). "Here, we show that the specific ablation of Foxp3+ Treg cells in DEREG mice can reproducibly precipitate severe insulitis and stable hyperglycemia in the context of a polyclonal TCR repertoire, provided that the autoimmune susceptibility is pre-installed by the NOD genetic background." (PMID 34447385, 2021). "In the analysis of the transcriptional factors of CD4+ T lymphocytes, the interaction between endotoxemia and hyperglycemia was not statistically significant in the effect on Tbx21 or Rorc, but was in the effect on Gata3 and Foxp3." (PMID 26207186, 2015).